ENSG00000260072 (novel transcript)
Synonyms: LOC105371143
Gene: Long non-coding RNA gene on chromosome 16 (24,465,805 to 24,495,184, reverse strand). Ensembl gene ENSG00000260072.
Gene Ontology:
Biological process: SRP-dependent cotranslational protein targeting to membrane, signal sequence recognition
Cellular component: signal recognition particle, endoplasmic reticulum targeting